CXCL9 (C-X-C motif chemokine ligand 9)
Diseases named in the same sentence as CXCL9 in open-access papers (continued):
Sharing a sentence is not in itself a finding about the gene and the disease.
vitiligo (continued). "CXCL-9 was sensitive and specific in diagnosing vitiligo disease severity." (PMID 35464413, 2022). "However, Stress 1 and Stress 2 populations were unique in stable vitiligo and expressed the highest levels of CXCL9/10." (PMID 35653192, 2022). "Indeed, HSP70i is the core participant in vitiligo predominantly through ﻿HSP70i-plasmacytoid dendritic cells (pDCs)-IFN-α-CXCL9 and CXCL10-cytotoxic T lymphocyte (CTL) axis." (PMID 36119071, 2022). "Typically, the accuracy of the blister fluid was only 87% in active vitiligo, while it was less than 50% in vitiligo in the treatment group; therefore, CXCL9 might serve as a good marker." (PMID 34521889, 2021). "Similar small-scale studies showed that the CXCL9 protein in the blister fluid achieved greater sensitivity and specificity in active vitiligo and might be an effective early marker of treatment response." (PMID 34521889, 2021). "Of them, CXCL9 is expressed the earliest in murine vitiligo lesions, and may be a more specific marker of disease activity." (PMID 34521889, 2021). "A central role of keratinocytes in vitiligo has recently emerged, as it is well documented that they are damaged and that these cells represent the predominant source of chemokines, such as CXCL9 and CXCL10, involved in the recruitment of T cells to vitiligo skin." (PMID 33126704, 2020). "However, addition of pre-stressed NKs or ILCs from vitiligo patients dramatically increased their own melanocyte production of CXCL9, CXCL10, CXCL11 and IFNγ." (PMID 31097717, 2019). "The result indicated that CXCL9 might induce recurrence of vitiligo." (PMID 39981245, 2025). "Recent studies have reported that the maintenance of decolorization of skin lesions in patients with vitiligo is simultaneously associated with autoreactive recirculating memory T (TRCM) cells in the blood, which bind to CXCR3 on the surface of TRCM cells via CXCL9 and CXCL10." (PMID 38779662, 2024). "Therefore, simultaneously targeting Trm cells and TRCM cells to block the CXCL9/10-CXCR3 pathway in vitiligo patients may be an effective strategy for treatment." (PMID 38779662, 2024). "Also, the CXCL9 level was a predictor of the effectiveness of CMT in treating vitiligo." (PMID 34521889, 2021). "Thus, it was hypothesized in this study that chemokines CXCL9 and CXCL10might be the potential biomarkers for predicting treatment response in patients with vitiligo undergoing CMT." (PMID 34521889, 2021). "Then, ROC curve analysis for IFN-γ, CXCL9, CXCL10, CXCL11 and IL-6 in recurrent versus persistent stable vitiligo were conducted." (PMID 39981245, 2025). "Elevated levels of these markers have also been found in patients with vitiligo, and the IFN-γ-CXCL9/10-CXCR3 axis is believed to play a central role in the progression and maintenance of the disease." (PMID 40861456, 2025). "JAK inhibitors, for instance, have shown the ability to reduce CXCL9 and CXCL10 levels, effectively controlling vitiligo progression." (PMID 40136446, 2025). "Recent research findings have identified multiple immune mechanisms and signaling pathways in the pathogenesis of vitiligo, including the JAK/STAT signaling pathway, the IFN-γ-CXCL9/10-CXCR3 pathway, Tregs, and tissue-resident memory T cells." (PMID 40136446, 2025). "Correlation analysis showed a positive relationship between IFN-γ, CXCL9, CXCL10, CXCL11, IL-6, and IL-15 in the plasma of patients with recurrent vitiligo." (PMID 39981245, 2025). "In agreement with the previous studies, our results also showed that the plasma levels of CXCL9 and CXCL10 are increased in vitiligo patients." (PMID 39981245, 2025). "To date, a number of clinical researches have reported that IFN-γ and its induced chemokines, CXCL9 and CXCL10, are related to disease activity, severity and prognosis in vitiligo." (PMID 39981245, 2025). "Serum CXCL9 (AA > vitiligo) and CXCL10 (AA = vitiligo) are elevated in both AA (N = 15) and vitiligo (N = 15) as compared with controls (N = 15)." (PMID 38673994, 2024).
vitiligo (continued). "CXCL9 and CXCL10 are expressed in many other skin diseases, and their functional importance was demonstrated for vitiligo, where inhibition of CXCL10 reduced recruitment of T cells and resulted in skin repigmentation." (PMID 39190494, 2024). "Previous work in vitiligo, an autoimmune disease characterized by CD8+ T cells targeting melanocytes, demonstrated an essential role for CXCL9 and CXCL10 in the recruitment of CD8+ T cells to skin." (PMID 39190494, 2024). "In both active and stable vitiligo, CXCL9 and CXCL10 were significantly higher than controls (p < 0.05), and they were significantly higher in active than stable vitiligo (p < 0.05)." (PMID 37762802, 2023). "Gene expression analysis of vitiligo lesions showed that interferon-γ (IFN-γ) and IFN-γ-induced genes, including T-cell chemokine receptor CXCR3 and its multiple ligands, such as CXCL9 and CXCL10 were significantly upregulated." (PMID 37207234, 2023). "CXCL9 and CXCL10 levels were significantly higher in patients (active and stable groups) than controls, and among the vitiligo patients, CXCL9 and CXCL10 levels were significantly higher in active than stable groups." (PMID 37762802, 2023). "The vitiligo mouse model in this study mimics many molecular features of human vitiligo, including upregulation of signature IFN-γ pathway genes (i.e., IFN-γ, CXCL9, and CXCL10)." (PMID 37925520, 2023). "We investigate the feasibility of IFN-γ, CXCL9, CXCL10, and GzmB as prognosis predictors for vitiligo." (PMID 35464413, 2022). "Studies found that CTLs secrete IFN-γ that induced keratinocyte secretion of CXCL-9 and CXCL10 which orchestrates the migration of T cells to the vitiligo lesion." (PMID 35464413, 2022). "This study identified that IFNγ-responsive fibroblasts can recruit CD8+ T cells through CXCL9 and CXCL10 in vitiligo." (PMID 35950754, 2022). "Consistently, the elevated levels of IFN-γ-inducible chemokines CXCL9 and CXCL10 in the serum or skin samples from vitiligo patients were confirmed in further studies." (PMID 35096274, 2022). "Keratinocytes secrete CXCL9 and CXCL10 to attract and activate CXCR3+CD8+ T cells, and these chemokines are present in the blister fluid of human vitiligo patients." (PMID 35653192, 2022). "The results show that IFN-γ, CXCL9, CXCL10, and GzmB are highly expressed in the skin blister interstitial fluid and plasma of vitiligo compared to healthy controls." (PMID 35464413, 2022). "Gene expression analysis of both human vitiligo skin and vitiligo mouse model skin revealed the upregulation of IFN-γ-specific signature, including chemokines CXCL10 and CXCL9, and their receptor CXCR3, which is expressed on T cells." (PMID 35432377, 2022). "Systematic investigation of cell-to-cell communication networks show that this small population of keratinocyte secrete CXCL9 and CXCL10 to potentially drive vitiligo persistence." (PMID 35653192, 2022). "Data we obtained examining patient sera suggest that, among the molecules that characterize the active phase of vitiligo, CD25 and CXCL9 represent independent predictive biomarkers of response to anti-PD-1 treatment." (PMID 35361879, 2022). "We further study the plasma expression of IFN-γ, CXCL9, CXCL10, and GzmB in active and stable vitiligo compared to healthy control." (PMID 35464413, 2022). "IFN-γ and its’ signature cytokines, including CXCL9, CXCL10, and GzmB, are most highly expressed in the vitiligo patients’ lesion skin interstitial fluid and plasma compared to healthy control." (PMID 35464413, 2022). "Our study showed that IFN-γ and its’ signature cytokines, including CXCL9 and CXCL10, and GzmB, are most highly expressed in the vitiligo patients’ blister and plasma compared to healthy control." (PMID 35464413, 2022). "CXCL9 and CXCL10 are CXCR3 ligands that are important for the recruitment of adaptive immune cells to the skin and progression of vitiligo." (PMID 35884944, 2022).
vitiligo (continued). "TYK2, another member of the JAK family, plays a ubiquitous role in signal transduction with type I interferon (IFN-α), which also induces the expression of CXCL9 and CXCL10 by keratinocytes in vitiligo." (PMID 34868078, 2021). "Receiver operating characteristic analysis revealed that the levels of CXCL9 and CXCL10 were sensitive and specific in diagnosing active vitiligo." (PMID 34521889, 2021). "This study found that the levels of CXCL9 and CXCL10 in the blister fluid were significantly higher in patients with active vitiligo than in patients with stable vitiligo." (PMID 34521889, 2021). "These include CXCL9, CXCL10, and CXCL11 and its receptor CXCR3, both in peripheral cells of the immune system and in the skin of patients diagnosed with vitiligo." (PMID 32992956, 2020). "In patients with vitiligo, the overexpression of chemokine receptors of the CXC family has been reported, namely CXCR3 and CXCR6, as well as the chemokines CXCL9, 10, and 11, natural ligands of CXCR3, and CXCL16, the only known natural ligand of CXCR6." (PMID 32992956, 2020). "Stimulation of healthy or vitiligo melanocytes with IFNγ induced a significant increase in mRNA expression of CXCL4, CXCL9, CXCL10 and CXCL11." (PMID 31097717, 2019). "Treatment with CXCL9 and CXCL11 also induced a significant melanocyte death in both healthy (P = 0.034 and P = 0.007, respectively) and vitiligo (P = P < 0.001 and P = 0.01) melanocytes that was almost completely prevented by the use of SiCXCR3B." (PMID 31097717, 2019). "Stimulation with IFNγ significantly increased both CXCL9 and CXCL10 protein in the supernatant of vitiligo melanocytes, producing on average 4–5 fold more chemokines compared to healthy controls." (PMID 31097717, 2019). "Additionally, IFN-γ, CXCL9, CXCL11, and IL-6 also exhibit substantial individual predictive capabilities for vitiligo recurrence, with AUC values of 0.806, 0.773, 0.785, and 0.709, respectively." (PMID 39981245, 2025). "Our results showed that, except for IL-15, the levels of these factors were significantly higher in recurrent patients compared to persistent stable patients, which suggest that increased levels of IFN-γ, CXCL9, CXCL10, CXCL11 and IL-6 are potential triggers for vitiligo recurrence." (PMID 39981245, 2025). "Based on previous research, we propose a hypothesis that IFN-γ, CXCL9, CXCL10, CXCL11, IL-6, and IL-15 are involved in the recurrence of vitiligo and are interconnected." (PMID 39981245, 2025). "In patients not achieving F-VASI50, CXCL9 and CXCL10 were the 5th and 15th most upregulating proteins which are both highly linked to vitiligo activity in numerous publications." (PMID 38715599, 2024). "CD8+ T lymphocyte toxicity is also an important component of vitiligo pathogenesis, therefore therapies blocking IFN-γ, the IFN-γ receptor, the ligands CXCL10 and CXCL9 and the receptor CXCR3 may also be worth exploring and testing in clinical studies." (PMID 37298700, 2023). "Moreover, keratinocytes secrete cytokines and chemokines including CXCL-9, CXCL-10, and IL-15 that amplify the inflammatory circuit within vitiligo skin and recruit melanocyte-specific, skin-resident memory T cells." (PMID 37275386, 2023). "However, the levels of IFNG, PRF1, GZMB and CXCR3, CXCL9, CXCL10, CXCL12, and other cytokines also had an upward trend in the vitiligo group." (PMID 37207234, 2023). "Again, KRT6A- and KRT16-expressing cells were found in healthy and nonlesional acute vitiligo skin, but these populations did not express CXCL9/10." (PMID 35653192, 2022). "IFN-γ, CXCL9, CXCL10, and GzmB are highly expressed in vitiligo patients’ lesion skin and plasma and may serve as biomarkers for the clinical activity, severity, and prognosis prediction in vitiligo patients." (PMID 35464413, 2022). "Many studies have shown that CXCL9 and CXCL10 are elevated in the suction blisters interstitial fluid and plasma analytes and act as potential biomarkers for differentiating between active and stable vitiligo." (PMID 35464413, 2022).
vitiligo (continued). "In conclusion, our results show that IFN-γ, CXCL9, CXCL10, and GzmB are highly expressed in vitiligo patients’ lesion skin and plasma and may serve as biomarkers for the clinical activity, severity, and prognosis prediction in vitiligo patients." (PMID 35464413, 2022). "The CXCL9 and CXCL10 levels in the blister fluid were related to the presence of active vitiligo." (PMID 34521889, 2021). "Additionally, a clinical study confirmed that CXCL9 and CXCL10 were positively correlated with disease activity in vitiligo patients." (PMID 33679890, 2021). "Intriguingly, of the mentioned cytokines and chemokines, many are reported to be biomarkers for vitiligo like IL‐1β, CXCL9, CXCL10, and CXCL16, which might aid vitiligo diagnosis and prognosis." (PMID 33200838, 2021). "It is well established that CXCL9 and CXCL10 are induced by IFNγ and function to promote effector T cell infiltration into tumors as well as sites of active depigmentation in the setting of vitiligo." (PMID 34362825, 2021). "CXCL9 and CXCL10 have been validated as the biomarkers of vitiligo activity." (PMID 34521889, 2021). "For example, CXCL9 and CXCL10 induced by IFN-γ play a key role in the skin migration of CD8+ T cells in vitiligo, and the expression of CXCR3 on melanocyte-specific CD8+ T cells has been detected in skin lesions and in the peripheral blood of vitiligo patients." (PMID 33679890, 2021). "The chemokine receptor CXCR3 (the receptor for the chemokines CXCL9 and CXCL10) was shown to be important for epidermal localization of effector T cells and TRM cell development, which led to studies on CXCR3 expression in vitiligo patients." (PMID 31230406, 2019). "Interestingly, CXCL9-induced melanocyte death was significantly lower compared with CXCL10-induced death in both healthy (P < 0.001) and vitiligo (P = 0.0035) patients." (PMID 31097717, 2019). "Furthermore, higher levels of CRP, IL-15, CXCL9, and CXCL10 are identified in active vitiligo." (PMID 37762802, 2023). "While mice with severe diseases exhibited a lack of higher expression of CXCL9, suggesting that CXCL9 may act more as a primary signal for T cell recruitment in vitiligo." (PMID 35096274, 2022). "Also, CXCL9 expression was found to be related to the treatment response, which might also be used to predict the response to CMT treatment in patients with vitiligo." (PMID 34521889, 2021). "The results showed that the differences in the type, location, stabilization time, and duration of vitiligo were not statistically significant, but the CXCL9 level in the blister fluid of 6 out of 11 patients was higher than 5000 pg/mL, close to the cutoff value of active vitiligo." (PMID 34521889, 2021). "IFN-γ, CXCL9, CXCL10, CXCL11, IL-6, and IL-15 were expressed at higher levels in the circulation of patients with both segmental and non-segmental vitiligo compared to healthy controls (p < 0.001)." (PMID 39981245, 2025). "IFN-γ signature chemokines, CXCL9 and CXCL10, are highly expressed in both lesion skin and non-lesion skin of vitiligo patients compared to healthy control with statistical significance." (PMID 35464413, 2022). "Moreover, in a mouse model of vitiligo, CXCL10-/- unlike CXCL9-/- mice did not develop depigmentation, indicating that the CXCL10-CXCR3 axis is responsible for this disease." (PMID 32977372, 2020).
colorectal cancer (37 papers, 2015 to 2025). A primary or metastatic malignant neoplasm that affects the colon or rectum. "CXCL9 is a T-cell chemoattractant and its expression in tumors is linked to improved response to immune checkpoint inhibition in patients with cancer and has also been associated with better prognosis in colorectal cancer." (PMID 36922934, 2022). "Additionally, a high expression of CXCL9 has been associated with a good survival rate after surgery in ovarian and colorectal cancers." (PMID 33854600, 2021). "Recent studies in mouse models of colorectal cancer have shown that IL-17 inhibits the production of the chemokines CXCL9 and CXCL10 by tumor cells, reducing the recruitment of CD8+ T cells." (PMID 41383591, 2025). "IL-17 can send signals to colorectal cancer cells and inhibit the production of CXCL9/10 chemokines." (PMID 34384424, 2021). "CXCL9 (chemokine ligand 9) mediates the recruitment of tumor-suppressive CXCR3+ T cells and NK cells and is significantly associated with improved prognoses for breast and colorectal cancers." (PMID 32513298, 2020). "On the other hand, immune-activating ligands that facilitate anti-tumor activity of CTLs, such as CXCL9 which is known to correlate with higher immune infiltrate and better prognosis in colorectal cancer, could also be uncovered from our screening methodology." (PMID 25691366, 2015). "In colorectal cancers, the expression of Cyclin G2 is significantly upregulated in macrophages in response to IFN-γ, leading to increased secretion of CXCL9, enhanced CTL chemotaxis, and inhibition of angiogenesis." (PMID 40909948, 2025). "Recent research utilizing murine lung and colorectal cancer cell lines reveals that Cyclin G2, a specific protein, is integral to the expression of the macrophage IFN-γ/JAK/STAT1/CXCL9 pathway." (PMID 40909948, 2025). "Studies have shown that in colorectal cancer, IGF2BP3 modulates the expression of T cell chemokines such as CCL5 and CXCL9/10, thereby influencing T cell recruitment to the tumor site." (PMID 41589308, 2025). "In the human colorectal cancer (CRC) cohort, SIN3B expression levels were significantly negatively correlated with CXCL9/10/11 as well as CD8A, GzmA, and GzmB." (PMID 39316363, 2024). "CXCL9/10/11 can recruit immune cells, including CD8+ T cells, Th1 cells, and NK cells, to reach tumor sites, thereby inhibiting the progression of colorectal cancer through the binding of CXCR3 protein to immune cell surface sites." (PMID 38275602, 2024). "CXCL9 is highly correlated with CD8 + T cells and natural killer (NK) cells in colorectal cancer and has an antitumour immune effect." (PMID 35292033, 2022). "This regulation occurs in part through the control of Th1-type chemokines, such as chemokine (C-X-C motif) ligand 9 (CXCL9) and CXCL10, which regulate effector T-cell recruitment to the colorectal cancer microenvironment." (PMID 34385592, 2022). "Conversely, ARID1A (BAF250A), a core member of the SWI/SNF complex, supports CXCL9 and CXCL10 expression in human colorectal cancer cells, resulting in enhanced recruitment of IFNγ-producing immune cells." (PMID 34385592, 2022). "Our result showed that high expression of CXCL9 and CXCL10 were correlated with a better prognosis, which is consistent with studies of colorectal cancer in recent years." (PMID 35251116, 2021). "CXCL9, CXCL10, CXCL11/CXCR3 axis has been proved to regulate immune cell migration, differentiation, and activation, leading to tumor suppression in pancreatic adenocarcinoma, colorectal cancer and so on." (PMID 34777466, 2021). "We demonstrate a negative correlation between EZH2 and class II expression in colorectal cancer in TCGA dataset, in addition to the negative correlation between EZH2 and CXCL9/10 described previously." (PMID 37565053, 2023). "Interestingly, high expression levels of CXCL9 and CXCL10 in colorectal cancer samples correlated with T cell infiltration, but not with NK cell infiltration that was scarce in the analyzed samples." (PMID 30319622, 2018).